EGFR (epidermal growth factor receptor)
Diseases named in the same sentence as EGFR in open-access papers (continued):
Sharing a sentence is not in itself a finding about the gene and the disease.
lung cancer (continued). "Because DNAJB1 can promote the growth of lung cancer by enhancing EGFR signaling through K48-linked ubiquitination of MIG6, modulation of DNAJB1 might provide a novel therapeutic approach." (PMID 36499297, 2022). "Furthermore, ERBB1/EGFR expression has been associated with resistance to immune checkpoint inhibitors (ICI) in lung cancer." (PMID 36311273, 2022). "ND-Cet can pull down EGFR in H1650 and H1975 lung cancer cells with EGFR mutations." (PMID 36678740, 2022). "In addition, evidence of its efficacy in patients with lung cancer and EGFR mutations was based on treatment with first- or second-generation EGFR tyrosine kinase inhibitor (TKI)." (PMID 36082280, 2022). "We hypothesize that the rich stroma of basal tumors contributes to anti-EGFR resistance, as recently demonstrated with cancer-associated fibroblasts in lung cancer." (PMID 36033544, 2022). "However, the basic question remains: what is the therapeutic mechanism underlying the effect of AICDA in EGFR-TKI-resistant lung cancer?" (PMID 35740609, 2022). "As is known to all, lung cancer patients with EGFR mutation, pathologically low differentiation, advanced pathological stage, and high Ki-67 index have a worse prognosis, which also suggests the potential prognostic value of the 7-AAB panel test to some extent." (PMID 36531072, 2022). "In addition, EphA2 expression is associated with EGFR inhibitor-resistant lung cancer cells, and combined treatment of EGFR and EphA2 targeted therapy is more effective than monotherapy in colorectal cancer and lung cancer." (PMID 35668076, 2022). "Therefore, the presence of different EGFR mutations in multiple lung cancers with the same or different histological characteristics must be considered, except when they are highly predicted to share the same molecular profiles, such as those of IPM." (PMID 35740676, 2022). "“Entropy” has been used for prognostic prediction in patients with high-risk oropharynx carcinoma after chemoradiation, in lung cancer patients after EGFR tyrosine kinase inhibitor treatment, and has been linked to treatment failure in metastatic colorectal cancer." (PMID 35053554, 2022). "We first used online databases and found that SIRT6 is upregulated in lung cancer, and the overall survival of lung cancer patients with high SIRT6 expression is shorter, suggesting that SIRT6 is associated with poor prognosis of lung cancer, especially EGFR mutant NSCLC." (PMID 35915188, 2022). "Taken together, these data suggest the genetic basis for germline EGFR mutations and somatic EGFR mutations in Chinese lung cancer patients is different and P/LP germline mutations unlikely account for predisposition of somatic mutations in EGFR in Chinese lung cancer patients." (PMID 35273153, 2022). "Proteobacteria was dominant in Thai lung cancer patients both EGFR-WT and EGFR-mutant, and this phylum maybe associate with lung cancer carcinogenesis." (PMID 36076157, 2022). "In July 2013, the College of American Pathologists/International Association for the Study of Lung Cancer/Association for Molecular Pathology (CAP/IASLC/AMP) released guidelines recommending that EGFR mutation testing be used to guide the choice of EGFR inhibitor treatment." (PMID 35397521, 2022). "We find EGFR-mutant lung cancers require few additional mutations to evolve a malignant phenotype." (PMID 36612014, 2022). "Shared constitutional genetic background and environmental exposure may result in multiple independent primary lung cancers with identical KRAS or EGFR mutations." (PMID 35008406, 2022). "Hence, it is worthwhile to further investigate the mechanistic roles of GPR155 I357S mutation in drug resistance of lung cancer patients especially EGFR-TKI." (PMID 35402275, 2022). "Thus, in lung cancer, ctDNA enables the detection of mutations that are potential therapeutic targets, such as epidermal growth factor receptor (EGFR) mutations." (PMID 36497340, 2022).
lung cancer (continued). "In other words, a lung cancer requires an EGFR mutation plus X addition gene mutations or a KRAS mutation plus Y additional gene mutations where Y > X. WT tumors, lacking any driver genes, require still more mutations (i.e., > Y mutations) to generate a malignant phenotype." (PMID 36612014, 2022). "Comparison of LiquidHALLMARK against the FDA-approved cobas EGFR Mutation Test v2 for 50 lung cancer specimens demonstrated an overall concordance of 84.00% (PPA 96.88%; NPA 61.11%), with eight discordant calls (LiquidHALLMARK VAF 0.05–0.33%) between LiquidHALLMARK and cobas." (PMID 35486650, 2022). "In accordance with previous studies, we also reported that 25% of patients with EGFR-mutated lung cancer had the T790M resistance mutation before EGFR-TKI treatment, and this pre-existing T790M mutation may negatively affect the drug’s efficacy." (PMID 35326664, 2022). "However, lung cancer cells with three mutations (EGFR-activating mutation/T790M/C797S) show resistant to third-generation EGFR-TKIs if the C797S and T790M mutations are both in the trans conformation." (PMID 35840984, 2022). "Correlation of EGFR mutation of lung cancer and ER status of breast cancer." (PMID 36313724, 2022). "However, EGFR mutation-positive lung cancer cases are diverse, with some likely to benefit from ICI treatment." (PMID 35407463, 2022). "Nonetheless, MET amplification is recognized as a mechanism of resistance following small-molecule inhibitor targeting of EGFR mutant lung cancer, and conversely, EGFR and HER3 amplification or mutation have been observed as resistance mechanisms to Met inhibition in human cancers." (PMID 35249128, 2022). "Similarly, HGF secreted by fibroblasts was implicated in lung cancer resistance to irreversible EGFR inhibitors and protected tumor cells from EGFR inhibitors in breast cancer cells bearing EGFR overexpression." (PMID 36324182, 2022). "In the current study, 570 patients with lung adenocarcinoma referred to the National Research Institute of Tuberculosis and Lung Diseases (NRITLD) were investigated for EGFR mutation to identify the frequency of this mutation among Iranian lung cancer patients." (PMID 35463723, 2022). "EGFR is mutated in 10–20% of lung adenocarcinomas among Caucasian patients and more commonly in young never-smoker Asian women, whereas EGFR mutations are rare in other lung cancer subtypes." (PMID 36011410, 2022). "Gefitinib is first generation drug for advanced lung cancer with a positive EGFR mutation." (PMID 35813479, 2022). "For instance, deletion of four highly conserved amino acids, LREA, in EGFR exon 19 and the L858R point mutation in exon 21 of lung cancer improves therapeutic response to EGFR-TKIs.15,16 (II) Genomic amplification and overexpression is the second major type of mutation." (PMID 36115852, 2022). "Importantly, lung cancer patients harboring an EGFR mutation possess a higher risk of CNS metastases." (PMID 35740489, 2022). "EGFR is also one of the most commonly mutated genes in lung cancer." (PMID 36074553, 2022). "In the coal-producing areas of East Yunnan, the G719X single mutation and G719X + S768I compound double mutations were principal EGFR gene types identified in the lung cancer patients, but other sensitive mutations (18-del, L861X, L833F, E709X, and EGFR gene amplification) were diverse." (PMID 35606799, 2022). "One of the biological changes that might be associated with lung cancer is the mutation of the EGFR oncogene." (PMID 35463723, 2022). "EGFR activating mutations has been implicated in pathogenesis of lung cancer." (PMID 35813479, 2022). "However, the activation and preservation of NSCLC are limited to relatively few oncogenic driver mutations, with EGFR as the most notable lung cancer oncogene." (PMID 36003330, 2022).
lung cancer (continued). "At present, the third generation EFGR-TKIs, such as Osimertinib or Aumolertinib, significantly improve response rates, progression-free survival (PFS), and overall survival (OS) in lung cancer patients with EGFR mutations, but the outcome of partial patients remains extremely poor." (PMID 36528578, 2022). "However, we noted that the 95% CIs of the estimates in association for vegetable consumption and lung cancer by EGFR status were largely overlapping, i.e., 0.69 (0.54–0.88) and 0.76 (0.58–1.01)." (PMID 36530673, 2022). "Given these, we hypothesized that PKCδ serves as the critical mediator for inducing immunosuppressive TME in EGFR-mutated lung cancer." (PMID 36482371, 2022). "However, even when that specific mutation is treated, EGFR-mut lung cancers access alternative genetic pathways to overcome therapy." (PMID 36612014, 2022). "Many patients with lung adenocarcinoma (LUAD), a major subtype of lung cancer, harbor mutations in the epidermal growth factor receptor (EGFR) in their cancer tissues and initially react well to molecular targeted drugs such as gefitinib, which inhibits EGFR tyrosine kinase (TKI)." (PMID 35301287, 2022). "The data suggest that complex interrelated pathways participate in the acquisition of EGFR-TKI resistance, and that modulating AICDA and NF-κB signaling may overcome limitations associated with treatment of EGFR-TKI-resistant lung cancers." (PMID 35740609, 2022). "Adverse events resulting from ICIs in EGFR-mutated lung cancer patients should be monitored." (PMID 35407463, 2022). "Thus, we assessed plasma ctDNA to quantitatively monitor variation in resistance-related clones while EGFR-mutated lung cancer patients were treated with EGFR-TKIs." (PMID 35326664, 2022). "For predicting EGFR mutations, our proposed brain metastasis-based LR-EGFR (AUCs of 0.750–0.850) outperformed previously proposed traditional radiomics models based on primary lung cancer (AUCs ranged from 0.575 to 0.762) and brain metastasis (AUCs ranged from 0.675 to 0.733)." (PMID 35991287, 2022). "Additionally, another study showed that the EGFR gene mutation frequency of patients with the different stages of lung cancer was markedly different." (PMID 35606799, 2022). "Molecular characterization has led to the definition of new subgroups such as lung cancer mutated for epidermal growth factor receptor, lung cancer rearranged for analytic lymphoma kinase and ROS1 kinase domain, and PDL1 expression, which need specific treatments and strategies." (PMID 35685154, 2022). "Moreover, ZEB1 represses HER3 promoter activity by suppressing NOTCH1 in EGFR-mutated lung cancer cells." (PMID 35042943, 2022). "One molecular mechanism possibly related to rapid tumor growth and the lack of response to brigatinib was the CDKN2A deletion detected in the third tumor rebiopsy, which promotes lung cancer progression and also impairs TKI responses in the similar constellation of EGFR-mutated lung cancer." (PMID 36207130, 2022). "These genes are enriched in mTOR and EIF2 signaling pathways, which the authors suggest might explain the activation of the mTOR pathway and EGFR-TKIs in lung cancers with EGFR mutations." (PMID 35205708, 2022). "Mutations of HER family members result in constitutive downstream pathway signaling and are found across a spectrum of cancers; the most common mutations include EGFR/HER1 activating mutations in non–small cell lung cancer (NSCLC) and HER2 amplifications/activating mutations in breast cancer (BC)." (PMID 35426374, 2022).
lung cancer (continued). "METex14 skipping mutation is considered to be an independent lung cancer driver, which is usually mutually exclusive with other lung cancer driver genes such as EGFR, ALK and ROS1, and is also associated with poor prognosis of lung cancer, including sarcomatoid cancer." (PMID 36212500, 2022). "Recent studies on the texture analysis of EGFR mutation status mainly focused on lung cancer." (PMID 35663041, 2022). "Epidermal growth factor receptor (EGFR) is one of the most common driver mutations of lung cancer." (PMID 35740489, 2022). "The EGFR gene is associated with cell growth and had a contribution in lung cancer studied before." (PMID 35632527, 2022). "As such reports are scarce, the aim of this study was to investigate the impact of pharmacological intervention for EGFR mutations in early-stage lung cancer on recurrence and prognosis in patients with NSCLC in order to find strong scientific evidence to support clinical decision-making." (PMID 36304772, 2022). "The present study is the first to report a higher rate of EGFR mutations in second primary lung cancer, which may play an important role in the development of double primary breast and lung cancer." (PMID 36313724, 2022). "Therefore, dynamic STMs can indicate molecular features in EGFR‐mutated lung cancer, including the emergence of secondary EGFR‐T790M and the EGFR ctDNA clearance." (PMID 35543090, 2022). "In addition to the identification of epidermal growth factor receptor (EGFR) tyrosine kinase inhibitors, the evaluation of the EGFR mutation status in lung cancer is important to devise optimal treatment strategies." (PMID 35740676, 2022). "Mutations in EGFR are associated with various cancers such as lung cancer and glioblastoma." (PMID 35715750, 2022). "However, further research is required to analyze the relationship between EGFR gene mutations in the coal-producing areas and the mechanisms of lung cancer." (PMID 35606799, 2022). "Although there have been previous reports regarding PD‐L1 expression in different histological and gene types of lung cancer, there are still few comprehensive studies on PD‐L1 expression of lung cancer in an endemic area with high epidermal growth factor receptor (EGFR) mutation such as Taiwan." (PMID 34841687, 2022). "Patients who experienced a second primary lung cancer exhibited a significantly higher rate of EGFR mutation (78.5%) than those with lung adenocarcinoma alone, with most exhibiting low-grade malignancy, older age, estrogen receptor negativity, low Ki67, and no lymph node metastasis." (PMID 36313724, 2022). "The prognostic model was first trained on a large dataset of 4106 CT-EGFR+ lung cancer patients to predict EGFR mutation status (wild type vs. mutant) based on the segmented lung region, and subsequently trained to detect COVID-19 in a separate dataset of 1266 patients." (PMID 35110593, 2022). "In this study we relied on screens that were set-up to resemble clinical treatment scenarios for EGFR mutant lung cancer, using NSCLC cancer cell lines harboring EGFR mutations commonly found in patient populations and where those cell lines were treated with 1st or 3rd generation EGFR inhibitors." (PMID 35351890, 2022). "Predicting the response to EGFR-TKIs for EGFR-mutated lung cancer patients is a key research area." (PMID 36344580, 2022). "Moreover, A significant portion (51.8%) of EGFR mutation positive lung cancer patients harbor low expression of ZNF24." (PMID 36457047, 2022). "WZ4002, a third-generation EGFR inhibitor, causes anoikis and inhibits lung cancer metastasis." (PMID 36230714, 2022). "For context, the discovery of the EGFR mutation in lung cancer was in 2004." (PMID 35805276, 2022). "Ongoing trials are testing several drugs (capmatinib, sotarasib, trastuzumab-deruxtecan and trastuzumab-emtasine) that are already used in clinical practice as a second line option for lung cancer and their benefit is not limited to the population with EGFR mutation." (PMID 36727053, 2022).
lung cancer (continued). "KRAS mutations and EGFR mutations are the main mutations driving the development of lung cancer." (PMID 36176446, 2022). "Interestingly, in the stratified analysis by EGFR status, a significantly decreased lung cancer risk was found only among EGFR+ lung cancer." (PMID 36530673, 2022). "In addition, targeted therapies have also been developed to treat patients with lung cancer harboring EGFR or anaplastic lymphoma kinase mutations." (PMID 35720364, 2022). "The estimation of the prevalence of EGFR Q787Q polymorphism in patients with lung cancer could be overestimated." (PMID 35387120, 2022). "EMT is also associated with EGFR-TKI resistance in lung cancer." (PMID 35790819, 2022). "Therefore, several studies have used radiomics models to noninvasively predict the EGFR mutation status of lung cancer or BMs using brain MRI." (PMID 35912248, 2022). "In this proof-of-concept study, we extracted radiomic features from multiple MRI sequence images (T1CE, T2WI, and T2 FLAIR) of excised BMs originating from lung cancer and used these features to build machine-learning models for the classification of EGFR mutation status in BMs." (PMID 35912248, 2022). "The difference could be explained by the high prevalence of EGFR mutation and smoking status in East-Asian patients with lung cancer." (PMID 36335353, 2022). "A study in 2018 revealed the frequency of 24.3% EGFR mutation among 103 lung cancer patients." (PMID 35463723, 2022). "Although several genes and pathways were detected to be potentially related to the occurrence of second primary lung cancer in breast cancer patients, it is well known that the incidence of lung adenocarcinoma is closely associated with some driver gene mutations like the EGFR mutation." (PMID 35668376, 2022). "Moreover, the gene amplification is detectable in 2–5% of NSCLC at first diagnosis and from 5% to 22% in patients with NSCLC with EGFR mutation following erlotinib/gefitinib and more than 20% of patients affected by lung cancer with brain metastases." (PMID 35069735, 2022). "TKI resistance in EGFR-mutated lung cancer cells may be due to a feedback loop between miR-630-YAP1-ERK due to a Bad down-regulation caused by ERK signaling-induced phosphorylation." (PMID 35264191, 2022). "However, both of these previous studies assumed an identical molecular profile in the BMs, thus overlooking possible discordances in EGFR mutation status between the lung cancer and the BMs." (PMID 35912248, 2022). "Determining the timing of EGFR mutations during carcinogenesis can predict whether multiple lung cancers share the same EGFR mutation or have different EGFR mutations." (PMID 35740676, 2022). "However, a graph visualization mask it hard to see a tertiary association e.g., drugs association with lung cancer with EGFR mutations." (PMID 35907849, 2022). "In addition, previous studies have demonstrated that the lungs exposed to coal-burning particles were a significant risk factor affecting EGFR gene mutations in the lung cancer patients." (PMID 35606799, 2022). "Moreover, in a study in mouse models of lung cancer with EGFR mutation, the TKI erlotinib was demonstrated to boost leukocyte infiltration and enhance antigen-presenting function." (PMID 35742933, 2022). "In conclusion, the association of the EGFR gene mutation with lung cancer has been indicated, so investigation of EGFR mutation could help decide about patients' therapeutic plan, such as anti-EGFR drug usage." (PMID 35463723, 2022). "The histological transformation into small cell or sarcomatoid lung cancer phenotypes, aberrations of drug transporters, or lysosomal sequestration has been reported for the mechanisms underlying the diminished efficacy of EGFR TKI." (PMID 35756605, 2022). "Likewise, epidermal growth factor receptor (EGFR)-mutated lung cancer patients had considerably increased miR-21 expression compared to those without mutations." (PMID 36139366, 2022).